AFP (alpha fetoprotein)
Diseases named in the same sentence as AFP in open-access papers (continued):
Sharing a sentence is not in itself a finding about the gene and the disease.
Cirrhosis (continued). "cHCC-CC is reportedly similar to HCC in terms of clinicopathologic characteristics including mean age, male/female ratio, hepatitis viral positivity, serum AFP level, and the presence of cirrhosis." (PMID 28183290, 2017). "A nomogram composed of age, sex, presence of cirrhosis, serum AFP levels and US findings better predicted the presence of HCC compared to US-only screening in CHB on surveillance." (PMID 29290966, 2017). "Multivariate analysis selected old age, male sex, presence of cirrhosis and high AFP as independent predictors of HCC presence in addition to the positive US findings." (PMID 29290966, 2017). "Single and combinational assessment of sAxl and AFP disclosed a better AUC of 0.937 for sAxl then for AFP (0.855) in HCC patients with cirrhosis." (PMID 28526812, 2017). "Both PIVKA-II and AFP levels were significantly elevated in HCC cases than cirrhosis and hepatitis groups (P < 0.001)." (PMID 28863782, 2017). "Age, sex, presence of cirrhosis, serum alpha-fetoprotein (AFP) levels and positive US test results were independent predictors of HCC presence." (PMID 29290966, 2017). "AFP levels is a most common used method for HCC surveillance, however, there are some HCC patients whose AFP levels constantly stay low or normal in clinical practice, and some patients with CHB and cirrhosis whose AFP elevated as false positive." (PMID 28827721, 2017). "The AUROC for the combination was 0.840 in differentiating HCC from cirrhosis and hepatitis, significantly higher than AFP alone (DeLong P < 0.001) and PIVKA-II alone (DeLong P = 0.018)." (PMID 28863782, 2017). "When using combinational eicosanoids and other metabolites to discriminate HCC from HBV-cirrhosis, the AUCs were 0.784 (eicosanoids) and 0.833 (metabolites), which was much better than that of AFP (0.657)." (PMID 28969038, 2017). "Diagnostic accuracy was further improved, if both sAxl and AFP were combined (HCC with cirrhosis: AUC 0.954; HCC w/o cirrhosis: AUC 0.941; cirrhosis: AUC 0.993)." (PMID 28526812, 2017). "Sex, BMI, tumor stage, tumor number, serum AFP levels, surgical safe margin and cirrhosis status were predictors of RFS in univariate analysis." (PMID 29176777, 2017). "In the stratified analysis, high PLCE1 expression increased the risk of recurrence and death among patients who were male and had early-stage BCLC, who had a single tumor, cirrhosis, AFP level > 300 ng/ml." (PMID 28418898, 2017). "Serum levels of ALP, GGT, TP, TC, AFP, hemoglobin (HGB), PLT were lower, but the MELD Score class and stage were higher in HBV-associated cirrhosis group than those in HBV-associated HCC group." (PMID 28198443, 2017). "The result suggested that parallel investigations of these metabolites exhibited higher sensitivity and specificity to distinguish HCC patients from healthy controls and HBV-cirrhosis patients, when compared with AFP." (PMID 28969038, 2017). "In fact, in a large-scale study enrolling 1377 patients with HCC and 355 with chronic hepatitis or cirrhosis, the diagnostic performance of DCP was inferior to that of AFP in terms of area under the ROC curves in small (<5 cm) HCC." (PMID 28620797, 2017). "In conclusion, a nomogram composed of age, sex, presence of cirrhosis, serum AFP levels and US findings better predicts the probability of presence of HCC compared to US-only screening in CHB on surveillance." (PMID 29290966, 2017). "HCC with BDTT is clinically featured as liver tumor with biliary dilation associated often with hepatitis B virus infection and to some extent with cirrhosis and has increased serum AFP and ALP levels." (PMID 28472122, 2017). "Different with the dramatic decrease of serum AFP in HCC patients with cirrhosis, the serum levels of GP73 remained stable resection of tumor tissue." (PMID 28157705, 2017). "Sex, BMI, BCLC stage, AFP levels and cirrhosis status were the independent predictors of RFS, while microvascular invasion was the independent predictor of OS." (PMID 29176777, 2017).
Cirrhosis (continued). "In future, further studies are needed to investigate factors such as serum AFP level and cirrhosis on the influences of recurrence and survival." (PMID 28816936, 2017). "The AUROC for the combination was 0.830 in differentiating HCC from cirrhosis, significantly higher than AFP alone (DeLong P < 0.001) and PIVKA-II alone (DeLong P < 0.001)." (PMID 28863782, 2017). "The development of HCC and/or hepatitis-related death are known to be predicted by the degree of fibrosis and inflammation, represented by cirrhosis, low platelet count, high AFP level, and high ALT level." (PMID 27478498, 2016). "Serum clusterin was introduced as more specific and sensitive biomarker than AFP in distinction of HBV-cirrhosis with HCC base on HBV-cirrhosis." (PMID 28224023, 2016). "High levels of plasma CCT3 protein were detected in HCC, and CCT3 had higher sensitivity (87.3 %) than AFP (69.8 %) in differentiating HCC from cirrhosis when the cut-off value was selected at 46.5 pg/mL and 20 ng/mL, respectively (P < 0.05)." (PMID 27390551, 2016). "Current guidelines are to suspect HCC in cirrhosis patients whose AFP level ≥400 μg/L for at least one month or ≥200 μg/L for at least two months." (PMID 27056898, 2016). "As expected, the clinical variables including ALT, AST, bilirubin, INR, albumin, AFP, and platelet count significantly differ between the fibrosis and cirrhosis groups." (PMID 27688741, 2016). "Blood samples were collected from 126 HCC patients with HCC, 88 patients with cirrhosis and 50 healthy volunteers to detect plasma α-fetoprotein (AFP), CCT3 and IQGAP3 levels." (PMID 27390551, 2016). "The combination of AST, GGT, AFP and platelet count was able to diagnose severe fibrosis and cirrhosis (F3-F4) in CHB patients with an AUC of 0.8533." (PMID 27731343, 2016). "We also did not detect correlations between high JARID2 expression in HCC tissues and gender, age, HBV infection, AFP, presence of cirrhosis, size of the tumor and presence of encapsulation." (PMID 27259236, 2016). "Taking preoperative IP VEGF-A as a reference, 10 baseline characters (age, sex, etiology, cirrhosis, tumor staging, tumor size, vascular invasion, previous interventions, resection type and serum AFP) were analyzed." (PMID 26930285, 2016). "When treatment related-factors during the follow-up period were additionally entered as time-dependent variables (Model 2), cirrhosis, AFP, and a recent high value of ALT were significantly associated with subsequent disease progression." (PMID 27478498, 2016). "In this study, high levels of plasma CCT3 protein were detected in HCC, and CCT3 had better sensitivity (87.3 %) than AFP (69.8 %) in differentiating HCC from cirrhosis." (PMID 27390551, 2016). "Intratumoral TLR3 positive rate was negatively related to the serum AFP levels (χ2 = 6.2411, P = 0.012) and positively related to HBsAg infection (χ2 = 9.5477, P = 0.002) and tumor with cirrhosis background (χ2 = 26.5278, P = 0.000)." (PMID 25983748, 2015). "Compared with the rs4969170 AA genotype, the rs4969170 GG genotypes were more frequently appeared in HCC patients with a higher serum AFP level (P = 0.004), advanced stage (P = 0.023), and cirrhosis rate (P = 0.001)." (PMID 26447993, 2015). "In most published papers OPN showed an advantage over AFP in the diagnosis of HCC in patients with cirrhosis due to HBV or HCV infections, with the best performance obtained by combining OPN and AFP." (PMID 26122937, 2015). "A recent study evaluating the effectiveness of HCC surveillance programs in patients with cirrhosis in a real-world clinical setting found that a combination of ultrasonography and AFP is the most effective strategy to detect early-stage HCC." (PMID 26398404, 2015). "Nearly one third of early HCC patients are missed by AFP analysis and it is also elevated in patients with chronic hepatitis and cirrhosis." (PMID 26352740, 2015).
Cirrhosis (continued). "The clinical characteristics, including age, sex, smoking status, serum AFP, tumor stage, tumor size, and cirrhosis are used as adjustment factor in COX analyses." (PMID 26447993, 2015). "Although elevated serum alpha-fetoprotein (AFP) can also be observed in patients with chronic liver disease without HCC, such as acute or chronic viral hepatitis, an increase in serum AFP in a patient with cirrhosis should raise the suspicion of HCC." (PMID 29201680, 2015). "36.3% (87/240) of these patients had an alpha-fetoprotein level more than 200 ng/mL and 47.9% (115/240) had a history of cirrhosis, 24.2% (58/240) had chronic active hepatitis, and 15% (36/240) had chronic persistent hepatitis." (PMID 26136615, 2015). "Nonetheless, there were no statistical connections between preoperative ALRI and other clinicopathological parameters including gender, family history, HBsAg, AFP, cirrhosis, tumor number, distant metastasis, and recurrence (all p > 0.05)." (PMID 26057470, 2015). "Multivariate analysis revealed that Child-Pugh B cirrhosis (P = 0.024) and a serum level of AFP >200 ng/mL (P = 0.039) were independent prognostic factors for overall survival." (PMID 25885683, 2015). "Sex, age, HBsAg, cirrhosis, serum AFP level, tumor size, tumor number, satellite nodules, tumor stage, vascular invasion, tumor metastasis, and type of resection (AR or NAR) did not influence recurrence." (PMID 25569656, 2015). "A typical HCC often accompanies hepatitis and hepatic cirrhosis, and the majority of patients have elevated serum AFP levels." (PMID 24944650, 2014). "Currently, abdominal ultrasound and alpha fetoprotein (AFP) tests are recommended for patients with cirrhosis every six months." (PMID 24999482, 2014). "Patients over 40 year old with risk factors such as hepatitis B, hepatitis C and cirrhosis are recommended to undergo HCC surveillance by ultrasonography and alpha-fetoprotein levels at 6-month interval." (PMID 25372403, 2014). "The most commonly used screening strategy in patients with cirrhosis is the determination of serum alpha-fetoprotein (AFP) levels." (PMID 25165471, 2014). "Expression of PDGFR-β correlated with alpha-fetoprotein level (P = 0.029), tumor size (P = 0.033), and hepatic cirrhosis (P = 0.023)." (PMID 23552472, 2013). "In terms of overall prediction of survival, the pretreatment PIVKA-II level, the presence of cirrhosis, the tumor number, and the AFP response were all independent predictors." (PMID 24455683, 2013). "Initially analyzed were the associations between mRNA status and available clinical information including age, gender, differentiation of the tumor, presence of hepatitis, presence of cirrhosis, tobacco, alcohol, AFP." (PMID 23347460, 2013). "It appears of much benefit in diagnosis, follow up and differentiation from cirrhosis in presence of low levels of alpha-fetoprotein." (PMID 23518665, 2013). "Univariate logistic regression analysis showed significant associations between cirrhosis and markers, including albumin, globulin, CHE, PT, INR, PLT, AFP, and CP (all P-values<0.05)." (PMID 24282481, 2013). "HCC surveillance with serum AFP level and ultrasonography has been recommended for patients with cirrhosis." (PMID 27335826, 2013). "The AFP level and the frequency of cirrhosis were significantly higher in the HCC group than in the CHB group." (PMID 23759077, 2013). "Highly significant increase was found in chronic hepatitis patients with steatosis than CHC without steatosis regarding necroinflammation as well as the severity of fibrosis/cirrhosis and AFP (P < 0.001)." (PMID 22675639, 2012). "The current standard of care in patients with cirrhosis includes HCC screening with six-monthly measurements of alpha-fetoprotein (AFP) level together with abdominal ultrasonography or computed tomography (CT)." (PMID 22559879, 2012). "There seems to be important correlations among the necroinflammation as well as the severity of fibrosis/cirrhosis and albumin with serum AFP." (PMID 22675639, 2012).
Cirrhosis (continued). "Variables including number and size of tumors, presence of metastases, serum alpha-Fetoprotein, hepatitis serologies, severity of hepatic dysfunction, and presence of cirrhosis were evaluated in 127 patients." (PMID 22681852, 2012). "The necroinflammation as well as the severity of fibrosis/cirrhosis and a lower serum albumin was shown to be predictor for elevation of serum AFP among chronic HCV with steatosis." (PMID 22675639, 2012). "AFP correlates with necroinflammation as well as the severity of fibrosis/cirrhosis in chronic HCV with steatosis." (PMID 22675639, 2012). "Significant correlations were found between AZGP1 expression and three parameters including serum AFP levels (P = 0.013), cirrhosis (P = 0.002) and tumor differentiation (P = 0.017)." (PMID 22625427, 2012). "Our results showed that serum AFP levels were correlated with the severity of periportal necroinflammation as well as the severity of fibrosis/cirrhosis among chronic HCV with steatosis." (PMID 22675639, 2012). "They increased both the number of HPC and the extent of the ductular reaction in addition to increased fibrosis/cirrhosis levels providing a potential mechanism whereby steatosis contributes to the increase in AFP." (PMID 22675639, 2012). "This indicated the special AFP promoter activity in liver cancer cells, though with slight activity in cirrhosis." (PMID 22040050, 2011). "Another tumour nodule of 2 cm was diagnosed based on characteristic CT findings, a history of chronic hepatitis B with cirrhosis and an abnormal AFP level." (PMID 22287986, 2011). "The correlation between CTSZ upregulation and clinical-pathological features including gender, age, HBsAg, serum AFP, tumor size, cirrhosis, adjacent organs invasion, reccurrence or metastasis, tumor encapsulation and tumor stage were studied." (PMID 21966391, 2011). "Univariate analysis demonstrated that serum albumin, cirrhosis, AFP, and portal vein obstruction (PVO) were prognostic factors of high statistical significance." (PMID 21176210, 2010). "In particular, IL-37 may complement AFP for HCC detection in decompensated cirrhosis, where conventional biomarkers often fail." (PMID 42073372, 2026). "However, its limited cirrhosis-HCC differentiation capacity (AUC = 0.70 vs AFP's AUC = 1.00) underscores HCV-specific microenvironmental influences on ZFAS1 regulation." (PMID 41450817, 2026). "Therefore, we think that the value of 5.49 for AFP in our study, which aims to diagnose cirrhosis patients with CHC only with a high number of patients and takes DAA therapy into account, is a very important auxiliary cut‐off for decision‐makers." (PMID 40384539, 2025). "Notably, variables such as age, sex, BMI, AFP level, cirrhosis, portal hypertension, Child–Pugh grade, and tumor proximity to large vessels and liver capsule did not demonstrate statistically significant correlations with OS and RFS (p > 0.05)." (PMID 40272237, 2025). "Guidelines recommend semi-annual HCC screening using abdominal ultrasound with or without alpha-fetoprotein (AFP) in high-risk individuals, including those with non-cirrhotic hepatitis B infection or cirrhosis from any etiology." (PMID 40040860, 2025). "The sensitivity of 18F-FDG PET/CT was associated with histologic grade (P < 0.001), while that of 18F-PSMA-1007 PET/CT was not correlated with those clinical and pathological features, such as cirrhosis, AFP levels, tumor number, MVI, or histologic grade (all P > 0.05)." (PMID 41438989, 2025). "The Milan group evaluated HCC surveillance by semiannual ultrasound evaluation and serum AFP determination in 258 patients with HBV-compensated cirrhosis who were receiving antivirals and had normal aminotransferases and normal serum AFP levels (≤7 ng/mL) at baseline." (PMID 40149352, 2025).
Cirrhosis (continued). "The incidence of HCC among HBV-HCV co-infected patients is noteworthy (20.98%), and there are strong correlations between the development of HCC and variables like age over 45, cirrhosis, length of infection, elevated AFP levels, and comorbidities such as diabetes, according to this study." (PMID 40662001, 2025). "Multiple researches showed that PON1 exhibits a strong diagnostic potential in distinguishing alpha-fetoprotein (AFP)-negative LIHC patients from those with AFP cirrhosis." (PMID 40662145, 2025). "In addition, when dealing with patients bearing advanced fibrosis/cirrhosis, it is very useful to determine AFP values after DAA therapy (probably best at the twelve-week post-treatment control)." (PMID 40149352, 2025). "Considering selected features, including TB, ALP, INR, AFP, age, sex, cirrhosis, and liver steatosis status, we believe that these laboratory and clinical parameters are usually available in the clinic, further supporting the clinical applicability of our models." (PMID 40231168, 2025). "We speculate that the detection of combined AFP with PUS1 possible produce an algorithm with better sensitivity for HCC patients with cirrhosis." (PMID 40171259, 2025). "Notably, for many of those destined to develop HCC, AFP levels had started rising around the time cirrhosis developed and prior to the achievement of SVR." (PMID 39516538, 2024). "Cox proportional hazard models were constructed in this study utilizing univariate and multivariate analyses that incorporated various variables, including surgical modality, age, sex, ALBI grade of liver function, tumor diameter, number of tumors, cirrhosis, and alpha‐fetoprotein (AFP) levels." (PMID 38488487, 2024). "Future guidelines could build on this by refining AFP and other biomarker cut-off values to account for factors like the cirrhosis stage, viral load, and patient demographics." (PMID 39682122, 2024). "No measurable differences were found for gender, age, hepatitis B, cirrhosis, BMI, history of alcohol consumption, alpha-fetoprotein (AFP), prothrombin time (PT), albumin (Alb), total bilirubin (TBil), alanine transaminase (ALT), aspartate transaminase (AST), and maximum diameter of the tumors." (PMID 39867901, 2024). "The National Viral Hepatitis Control Program recommends routine HCC surveillance with abdominal ultrasound and alpha-fetoprotein testing every 6 months for individuals with cirrhosis, a family history of HCC, an age of more than 40 years and an elevated HBV DNA level of more than 2,000 IU/mL." (PMID 39430076, 2024). "Recent studies have reported that patients with certain benign liver diseases (such as active hepatitis and cirrhosis) might also exhibit elevated levels of AFP in their blood." (PMID 38952558, 2024). "Surveillance for HCC among patients with HCV cirrhosis has been demonstrated to be cost-effective using either semiannual AFP and annual US or triple-phase computed tomography (CT) compared to no surveillance, with the cost of surveillance being less than $50,000 per quality-adjusted life year." (PMID 39319076, 2024). "Furthermore, negative correlation was seen between the levels of TH protein and the tumor size, tumor number, the level of AFP, as well as cirrhosis." (PMID 38610044, 2024). "In addition, decreased TH indicated larger tumor size, much more numbers of tumor, higher level of AFP, and the presence of cirrhosis." (PMID 38610044, 2024). "However, the AFP level is also increased under pregnancy, hepatitis, cirrhosis and other benign diseases." (PMID 36733504, 2023). "OPN even outperforms AFP in distinguishing cirrhosis from liver cancer." (PMID 37575092, 2023). "Routine screening for HCC with ultrasound (US) and alpha fetoprotein (AFP) serum levels are recommended in patients with cirrhosis and high-risk patients without cirrhosis but with chronic HBV." (PMID 38136295, 2023). "This was also true for AFP, which had a high false positive rate in hepatic cirrhosis." (PMID 37525116, 2023).